MRPL14 (mitochondrial ribosomal protein L14)
Description:
Forms part of 2 intersubunit bridges in the assembled ribosome. Upon binding to MALSU1 intersubunit bridge formation is blocked, preventing ribosome formation and repressing translation (Probable).
Synonyms: L14mt; MRP-L14; L32mt; MRP-L32; RPML32; uL14m; RMPL32
Tractability: Small molecule: a structure with a bound ligand is known. PROTAC: its protein half-life has been measured.
Gene: Protein-coding gene on chromosome 6 (44,112,290 to 44,128,724, reverse strand). Ensembl gene ENSG00000180992.
Subcellular location: Mitochondrion
Subcellular location (Human Protein Atlas): Mitochondria
Pathways (Reactome):
Metabolism of proteins: Mitochondrial ribosome-associated quality control; Mitochondrial translation elongation; Mitochondrial translation initiation; Mitochondrial translation termination
Gene Ontology:
Molecular function: RNA binding; structural constituent of ribosome
Biological process: mitochondrial translation; translation
Cellular component: mitochondrial large ribosomal subunit; mitochondrion; mitochondrial inner membrane; ribosome
Genetic constraint (gnomAD): Loss-of-function variants: 8 observed, 10.21 expected, observed/expected ratio (o/e) 0.78, 90% interval 0.46 to 1.41. The upper end of that interval is the gene's LOEUF score, 1.41, which puts it in group 5 of 6, group 1 being the genes least tolerant of losing a copy. Missense variants: 137 observed, 156.71 expected, observed/expected ratio (o/e) 0.87, 90% interval 0.76 to 1.01. Synonymous variants: 62 observed, 60.1 expected, observed/expected ratio (o/e) 1.03, 90% interval 0.84 to 1.27.
Homologues: Orthologues: chimpanzee MRPL14 (99% identical), macaque MRPL14 (96% identical), dog MRPL14 (88% identical), mouse Mrpl14 (85% identical), rat Mrpl14 (84% identical), guinea pig MRPL14 (82% identical), tropical clawed frog mrpl14 (70% identical), zebrafish mrpl14 (67% identical), Drosophila melanogaster mRpL14 (47% identical). Paralogues in human: C1orf53 (12% identical).
Diseases named in the same sentence as MRPL14 in open-access papers:
MRPL14 is named in the same sentence as 14 diseases in open-access papers, as found by Europe PMC text mining. Sharing a sentence is not in itself a finding about the gene and the disease. The quoted sentences say what the papers report.
diabetes retinopathy (2 papers, 2020 to 2024). "The MRPL14 single nucleotide polymorphism may be related to diabetic retinopathy through steroid metabolism or insulin resistance." (PMID 33193718, 2020). "MRPL14 not only promotes the biogenesis and mitochondrial translation of mitochondrial macroribosomal subunits, but also has certain relevance in diabetes retinopathy." (PMID 40625890, 2024).
ovarian carcinoma (2 papers, 2021 to 2024). A malignant neoplasm originating from the surface ovarian epithelium. "PKM2, MRPS12, NDUFC2, HPDL, MRPL14, COA6 and RNF144B were significantly upregulated in ovarian cancer, but the down-regulation of NDUFC2, HPDL, MRPL14, COA6 and RNF144B was associated with poor prognosis in patients with ovarian cancer." (PMID 39478854, 2024). "PKM2, MRPS12, NDUFC2, HPDL, MRPL14, COA6 and RNF144B were significantly upregulated in ovarian cancer tissues than in normal tissues (P < 0.05), while RPL23, FGFR1OP2, CAPN10, ALDH1L1 and ACSM1 were significantly down-regulated (P < 0.05)." (PMID 39478854, 2024).
thyroid tumor (2 papers, 2020 to 2023). A benign or malignant neoplasm affecting the thyroid gland. "MRPL14 is part of 2 intersubunit bridges in the assembled ribosome, which might be involved in the occurrence and development of thyroid tumors." (PMID 37223030, 2023). "MRPL14 is highly expressed in thyroid tumor, but does not reveal the relationship with prognosis." (PMID 33193718, 2020).
asthma (1 paper, 2023). "Moreover, the differentially co-expressed genes, both up- and down-regulated in EA, were previously linked to asthma in the genome- (e.g., MRPL14, ASB3, RHOBTB2) and epigenome-wide (e.g., CLC, EPS15, GPI, SRCRB4D, STRN4) association studies." (PMID 36835202, 2023). "Among the differentially co-expressed genes, eight were previously linked to asthma in genome- (MRPL14, ASB3, RHOBTB2) and epigenome-wide (CLC, EPS15, GPI, SSCRB4, STRN4) association studies and five were mentioned in the literature in the context of asthma (SLC19A1, MAEA, CLC, ATP1B1, and RECK)." (PMID 36835202, 2023).
Blindness (1 paper, 2021). Blindness is the condition of lacking visual perception defined as a profound reduction in visual perception. "For example, MRPL2, MRPL14, MRPS10, MRPS18A, and MRPS18B are candidate genes for spinocerebellar ataxia with blindness and deafness." (PMID 34987545, 2021).
breast tumor (1 paper, 2022). "GPX-1 and MRPL14 mRNAs are also depleted (>60%) from human breast tumor MCF-7 cells (GPX-2 is not expressed in MCF-7 cells)." (PMID 35104504, 2022).
ovarian tumor (1 paper, 2024). "The role of genes encoding such proteins, LUC7L2, MRPL46, MRPL14, PARP4, STRAP, and PAPOLA, in ovarian tumor development has already been investigated in the literature." (PMID 39456618, 2024).
pancreatic tumor (1 paper, 2023). "However, the role of COQ4, MCRIP2, MRPL50, MRPL14, RFK, and NMNAT3 in pancreatic tumor has not been reported." (PMID 37223030, 2023).
thyroid cancer (1 paper, 2025). "MRPL14 accelerates the proliferation and migration of thyroid cancer cells by promoting the expression of EMT-related proteins." (PMID 40371222, 2025). "MRPL14 also exhibits significant oncogenic effects in thyroid cancer." (PMID 40371222, 2025).
cancer (1 paper, 2023). A tumor composed of atypical neoplastic, often pleomorphic cells that invade other tissues. "However, research on the role of MRPL14 in cancers is currently still blank." (PMID 36778919, 2023).
MRPL14 also shares sentences with these, for which no sentence is quoted: deafness (1 paper); Insulin resistance (1); spinocerebellar ataxia (1); tumor (1).